PRANCR (progenitor renewal associated non-coding RNA)
Synonyms: CNOT2-DT; LINC01481
Gene: Long non-coding RNA gene on chromosome 12 (69,901,918 to 70,244,533, reverse strand). Ensembl gene ENSG00000257815.
Diseases named in the same sentence as PRANCR in open-access papers:
PRANCR is named in the same sentence as 6 diseases in open-access papers, as found by Europe PMC text mining. Sharing a sentence is not in itself a finding about the gene and the disease. The quoted sentences say what the papers report.
ovarian carcinoma (2 papers, 2021 to 2023). A malignant neoplasm originating from the surface ovarian epithelium. "For instance, MYRF-AS1 was associated with genomic instability and is considered a risk factor in Non-small cell lung cancer, while PRANCR is up-regulated in primary ovarian cancer and SCL25A5-AS1 was associated with the bladder cancer growth." (PMID 38003837, 2023). "Moreover, in human, lncRNA PRANCR is closely related with epidermis formation and ovarian cancer metastasis." (PMID 34895356, 2021).
mastitis (1 paper, 2021). Inflammation of breast tissue during lactation or postpartum due to an obstructed duct or infection. "lncRNAs PRANCR and TNK2–AS1 could be regarded as stable markers associated with bovine S. aureus mastitis." (PMID 34895356, 2021).
cancer (2 papers, 2023). A tumor composed of atypical neoplastic, often pleomorphic cells that invade other tissues. "PRANCR and DLEU2 were also down-regulated and are associated with cell proliferation and cancer progression." (PMID 37624890, 2023). "Moreover, the most up-regulated lncRNA genes found in the infected samples—MYRF-AS1, ATP2A1-AS1, CTC-338M12.4, MESTIT1, PRANCR, and SLC25A5-AS1—are associated with several types of cancers in a conflicting manner." (PMID 38003837, 2023).
PRANCR also shares sentences with these, for which no sentence is quoted: bladder cancer (1 paper); ischemic stroke (1); non-small cell lung carcinoma (1).